CDK4 (cyclin dependent kinase 4)
Diseases named in the same sentence as CDK4 in open-access papers (continued):
Sharing a sentence is not in itself a finding about the gene and the disease.
synovial sarcoma (18 papers, 2013 to 2025). "Collectively, these results indicate that reduced synovial sarcoma cell proliferation by inhibition of CDK4/6-Rb pathway is associated with induction of cell cycle arrest and cell apoptosis." (PMID 29670090, 2018). "In addition, the CDK4 pathway has been newly mutated in our brain metastasis samples of Clear cell RCCs and not in primary tumor cells, while tumors of neuroendocrine carcinoma, synovial sarcoma and keratinizing SCCs show mutations only in their primaries." (PMID 36507516, 2022). "In contrast, synovial sarcomas (SS) frequently exhibit overexpression of CDK2, CDK4, and MDM2, loss of CDKN2A, and mutations in genes such as CDK 4/6." (PMID 38275873, 2024). "In the current study, we explore the expression and function of the CDK4/6-Rb pathway in synovial sarcomas, and investigate the therapeutic potential of the selective CDK4 inhibitor, palbociclib, in vitro." (PMID 29670090, 2018). "Of the 50 TMA cases of synovial sarcoma, 41 (82.0%) of the tissues express detectable CDK4 expression." (PMID 29670090, 2018). "CDK4 inhibition decreases synovial sarcoma cell proliferation and growth through apoptosis induction via cell cycle arrest." (PMID 29670090, 2018). "As demonstrated by western blotting, all these human synovial sarcoma cell lines exhibit high levels of CDK4 expression." (PMID 29670090, 2018). "The results revealed that CDK4 inhibition dramatically induced cell cycle arrest in G1 phase in synovial sarcoma cells after palbociclib treatment." (PMID 29670090, 2018). "Knockdown of CDK4 with specific small interference RNAs inhibits cell proliferation and enhances apoptotic effects in synovial sarcoma cells." (PMID 29670090, 2018). "This suggests that CDK4/6-Rb inhibition, induced by palbociclib, is able to promote G1 cell-cycle arrest and inhibit DNA synthesis in synovial sarcoma cells." (PMID 29670090, 2018). "The IHC results demonstrate that CDK4 immunoreactivity is in the nucleus of synovial sarcoma tissue cells." (PMID 29670090, 2018). "The result showed that CDK4 inhibition by siRNA decreased synovial sarcoma cell proliferation and growth in a dose-dependent manner." (PMID 29670090, 2018). "Cell apoptosis determination simultaneously revealed that CDK4 inhibition dramatically induced cell apoptosis in synovial sarcoma cells." (PMID 29670090, 2018). "To validate the effect of CDK4/6-Rb pathway in synovial sarcomas in vitro, we knocked down expression of CDK4 using two CDK4 specific siRNAs." (PMID 29670090, 2018). "CDK4 inhibitor palbociclib suppresses synovial sarcoma cell proliferation and growth in a dose and time-dependent manner." (PMID 29670090, 2018). "As shown, CDK4 protein is mostly localized in the nucleus of synovial sarcoma cells, but with some localized to the cytoplasm." (PMID 29670090, 2018). "Consistently, our findings demonstrated that CDK4 inhibition by palbociclib reduced synovial sarcoma cell proliferation and growth dose-dependently." (PMID 29670090, 2018). "Flow cytometry analysis reveals that palbociclib induces G1 cell-cycle arrest and apoptotic effects by targeting the CDK4/6-Rb pathway in synovial sarcoma cells." (PMID 29670090, 2018). "We first analyzed the expression levels of CDK4 in synovial sarcoma cell lines and found that CDK4 was highly expressed in all the human synovial sarcoma cell lines, and it was found to be localized to the nucleus by immunofluorescence staining." (PMID 29670090, 2018). "We further suppressed the expression of CDK4 in synovial sarcoma cells using the clinically approved CDK4 inhibitor, palbociclib, and explored changes to the cellular phenotypic." (PMID 29670090, 2018). "Our study highlights the importance of the CDK4/6-Rb pathway in human synovial sarcoma pathogenesis, and the role of the current selective CDK4/6 inhibitor, palbociclib, as a potential promising targeted therapeutic agent in the treatment of human synovial sarcoma." (PMID 29670090, 2018).
synovial sarcoma (continued). "Taken together, our current study demonstrates that CDK4 is highly expressed in synovial sarcomas." (PMID 29670090, 2018). "We then further analyzed the effect of CDK4 inhibition on synovial sarcoma cell migration in vitro." (PMID 29670090, 2018). "Furthermore, wound healing assays demonstrate that inhibition of the CDK4/6-Rb pathway by palbociclib significantly decreases synovial sarcoma cell migration in vitro." (PMID 29670090, 2018). "Therefore, in this study, we evaluate the expression of CDK4 and its therapeutic applications in human synovial sarcoma, as well as test palbociclib as a possible treatment for synovial sarcoma." (PMID 29670090, 2018). "This suggests that CDK4 may play an important role in the pathogenesis of synovial sarcoma." (PMID 41155410, 2025). "Synovial sarcoma cells treated with non-lethal doses of palbociclib unveiled that CDK4 inhibition reduced synovial sarcoma cell migration, suggesting that CDK4 might be a promotor to synovial sarcoma metastasis, which is the main obstacle in the treatment of synovial sarcoma." (PMID 29670090, 2018). "Hence, these findings confirmed that CDK4 inhibition, triggered by palbociclib, could decrease synovial sarcoma cell proliferation and growth via induction of cell apoptosis via arresting the cell cycle in G1 phase." (PMID 29670090, 2018). "However, the expression and therapeutic potential of targeting CDK4 in synovial sarcoma remains unclear." (PMID 29670090, 2018). "This suggests CDK4 might have an important role in the pathogenesis of synovial sarcoma." (PMID 29670090, 2018). "CDK4 is a member of the cyclin-dependent kinase (CDK) 4/6-retinoblastoma protein (Rb) pathway that is altered in many human cancers, including synovial sarcoma, and has been found to be focally amplified in OS." (PMID 33407928, 2021). "Relative expressions of CDK4 and CDK6 were compared with β-actin in different synovial sarcoma cell lines." (PMID 29670090, 2018). "However, as a critical part of the Cyclin D/CDK4/6/Rb axis, the expression and clinical significance of CDK4, and the potential mechanism of targeting CDK4 using the specific inhibitor palbociclib as a putative therapeutic strategy, remains to be elucidated in synovial sarcoma." (PMID 29670090, 2018). "Consistent with the inhibition of G1-to-S phase progression, we found decreased cyclin D1 expression and decreased phosphorylation of CDK4 and CDK2 in synovial sarcoma cells in response to SAHA, LBH-589, and PXD101." (PMID 29100385, 2017). "However, we find that CDK4 expression significantly correlated with the clinical stage and TNM grade of the synovial sarcoma (both P < 0.05)." (PMID 29670090, 2018).
medulloblastoma (16 papers, 2015 to 2026). A malignant, invasive embryonal neoplasm arising from the cerebellum. "Another molecular axis involving HOTAIR, miR-483-3p, and CDK4 is strongly associated with medulloblastoma progression." (PMID 33540611, 2021). "Various CDK inhibitors are already FDA-approved for treatment of different types of metastatic cancers and CDK4/6 inhibition has been shown to inhibit tumor growth of medulloblastoma cells in vivo." (PMID 39043693, 2024). "In a high-throughput drug screen, BRD4 inhibitors have been found to be one of the two classes of compounds exerting the best synergistic anticancer effects with the CDK4/CDK6 inhibitor Ribociclib in medulloblastoma cells." (PMID 38135679, 2023). "A reverse combination drug screen identifies CDK4/CDK6 inhibitors as the compounds exerting the best synergy with the BRD4 inhibitor JQ1 against medulloblastoma cells." (PMID 38135679, 2023). "On the contrary, HOTAIR silencing inhibits cell proliferation and promotes cell apoptosis in medulloblastoma cells by upregulation of miR-483-3p and downregulation of CDK4, respectively." (PMID 33540611, 2021). "For instance, in the SJDAWN phase 1 clinical trial (NCT03434262) both group 3 and group 4 tumors belong to the same arm receiving ribociclib combined with gemcitabine although the efficacy of CDK4/6 inhibitors has only been proven in preclinical models of group 3 medulloblastoma." (PMID 37568705, 2023). "Mechanistic studies in medulloblastoma cells, Daoy and D341 as well as medulloblastoma xenograft mice models to discern the exact molecular mechanisms/players behind the pro-tumorigenic actions of HOTAIR revealed possible involvement of the miR-483-3p-CDK4 axis." (PMID 38366205, 2024). "In vitro study has demonstrated that VPA induces histone (H3 and H4) hyperacetylation, activates p21, restore p16/CDK4 pathway and suppresses CMYC oncogene in medulloblastoma (DAOY and D283-MED) cell lines." (PMID 31030484, 2019). "Furthermore, consistent with the growth arrest of the cells in the G0/G1 phase, the expression of p16, a CDK4/CDK6 inhibitor, was found to be upregulated in medulloblastoma cells upon miR-193a expression." (PMID 32410663, 2020).
head and neck squamous cell carcinoma (15 papers, 2015 to 2025). A squamous cell carcinoma that arises from any of the following anatomic sites: lip and oral cavity, nasal cavity, paranasal sinuses, pharynx, larynx, and salivary glands. "In a targeted therapy context, metformin can synergistically enhance the in vitro and in vivo antiproliferative effects of CDK4/6 inhibition in experimental models of head and neck squamous cell carcinoma (HNSCC)." (PMID 33494247, 2021). "Moreover, Cyclin D1 and CDK4 downregulation through syntenin depletion was previously reported in head and neck squamous cell carcinoma." (PMID 26539120, 2015). "Another investigation showed that METTL1 facilitated the growth of head and neck squamous cell carcinoma (HNSCC) cells by stabilizing Cyclin Dependent Kinase 4 (CDK4) mRNA, a critical regulator of the cell cycle." (PMID 40809384, 2025). "The expression of CDK4 gene in P-Tex2 cluster is associated with the treatment outcomes of HPV+ head and neck squamous cell carcinoma (HNSCC) patients." (PMID 36811599, 2023). "For instance, palbociclib and abemaciclib, which are inhibitors of the cell cycle-related kinases CDK4 and CDK6, show an anti-tumor effect in a patient-derived xenograft (PDX) model of head and neck squamous cell carcinoma (HNSCC)." (PMID 32610557, 2020). "Further studies of CDK4/6 inhibitors are warranted in non-HPV-related head and neck squamous cell carcinoma." (PMID 40864763, 2025).
meningioma (15 papers, 2008 to 2026). A generally slow growing tumor attached to the dura mater. "Cell viability assay demonstrated that these primary Rb-deficient meningioma cell lines were resistant to treatment with selective CDK4/6 inhibitors abemaciclib and palbociclib at escalating doses." (PMID 37093270, 2023). "Thus, the synergy we observed between Nf2 and p16Ink4 mutations in meningioma development reflects the concomitant loss of two regulators of CDK4 activity resulting in cyclin D1 activation." (PMID 17924978, 2008). "We evaluated the efficacy of abemaciclib, a cyclin-dependent kinase 4/6 inhibitor, as one arm of the Alliance umbrella trial A071401, a genomically driven phase 2 study in recurrent and progressive meningiomas." (PMID 41545592, 2026). "CDK4 and cyclin D3 drive meningioma cells into the S phase and enhance cell proliferation and migration." (PMID 38398158, 2024). "This interaction promotes the transcription of cell cycle genes CDK4 and cyclin D3 through the activation of the NF-κB pathway, thereby enhancing the proliferation of meningioma cells." (PMID 38398158, 2024). "Transcriptome sequencing data analysis revealed that RACK1 knockdown significantly downregulated the cell cycle pathway in meningioma cells, with CDK4 and cyclin D3 being the most affected." (PMID 38398158, 2024). "Although CDKN2A normally negatively regulates CDK4, there was significantly higher CDK4 mRNA expression in CDKN2Ahigh meningiomas compared to CDKN2Alow cases across all cohorts." (PMID 37093270, 2023). "Like p16, CDKN2Ahigh meningiomas had the highest abundance of CDK4 protein compared to all other groups." (PMID 37093270, 2023). "As both CDKN2A and CDK4 expression were elevated in CDKN2Ahigh meningiomas, we correlated these changes with DNA methylation at their respective loci." (PMID 37093270, 2023). "Preclinical evidence supports the use of CDK4/6 specific inhibitors, Palbociclib, Abemaciclib, and Ribociclib, as potential therapeutic agents for meningioma patients and these agents are actively being explored in ongoing clinical trials." (PMID 35936751, 2022). "Misactivation of the cell cycle at the level of CDK4/6 is common in high-grade or molecularly aggressive meningiomas, and CDK4/6 has emerged as a potential target for systemic meningioma treatments." (PMID 35936751, 2022). "Using Grade 1 and Grade 3 meningioma cell lines, Palbociclib treatment inhibited the expression of CDK4/6 and downstream E2F transcription factor, resulting in dramatic reduction of pRB and reduced cell proliferation." (PMID 35936751, 2022). "Therefore, when tested, CDK4/6 inhibitors, which target a key cell cycle checkpoints, were found to effectively attenuate cell growth of HM meningiomas in vitro." (PMID 36840836, 2023). "Thus, vismodegib or sonidegib are currently tested in combination with either the focal adhesion kinase inhibitor GSK2256098, the AKT-inhibitor capivasertib or the CDK4/6-inhibitor abemaciclib in the treatment of meningioma (NCT02523014)." (PMID 37476499, 2023). "Pharmacological inhibition of cyclin-dependent kinases CDK4/6 could represent a particularly promising strategy in higher-grade meningiomas with high mitotic activity independently from CDKN2A/B status." (PMID 36181606, 2023). "Two ongoing trials investigating ribociclib and one investigating abemaciclib as selective inhibitors of CDK4 and CDK6 are investigating the role of CDK inhibitors in treating meningiomas (NCT02933736, NCT03220646, NCT02523014)." (PMID 36672431, 2023). "Our results demonstrate hyperphosphorylation of RB1 Ser780 and increased CCND1, CDK4, and CDK6 expression in high-grade meningiomas and after AKAP12 knockdown." (PMID 29391485, 2018). "However, unlike at the transcriptomic level, where meningiomas with CDKN2A homodel had the highest CDK4 expression, CDKN2A homodel meningiomas showed lower levels of CDK4 protein, although only 3 tumors in this group were profiled here." (PMID 37093270, 2023).
meningioma (continued). "Furthermore, nearly one third of all WHO grade 3 meningiomas have CDKN2A/B deletions, which necessitates further research on markers identifying patients who might benefit from CDK4/6 inhibitors." (PMID 38017560, 2023). "This suggests that a subset of patients with CDKN2Ahigh meningiomas may not respond to CDK4/6 inhibitors if they do fail surgery and radiotherapy." (PMID 37093270, 2023).
mesothelioma (15 papers, 2009 to 2025). A usually malignant and aggressive neoplasm of the mesothelium which is often associated with exposure to asbestos. "Several reports have already linked CDK4 expression to mesothelioma." (PMID 20043850, 2009). "Phospho‐CDK4 is nevertheless detected in most mesotheliomas, which should be sensitive to CDK4/6 inhibitors." (PMID 36453028, 2024). "Nearly all mesothelioma tumors will exhibit deregulated G1/S cell cycle control (Rb-intact), but only a few attempts have been made to evaluate CDK4/6 inhibition in mesothelioma." (PMID 37298855, 2023). "Combination therapy with inhibition of mitochondrial antioxidant defense and CDK4/6 holds promise as a potential therapeutic strategy in mesothelioma." (PMID 37298855, 2023). "Preclinical studies of CDK4/6 inhibitors showed encouraging results in mesothelioma cell lines and xenografts, but with limited efficacy in a Phase II clinical trial (NCT02187783)." (PMID 36138075, 2022). "Given that CDKN2A is deleted in approximately 45% of mesothelioma cases, palbociclib, a CDK4/6 kinase inhibitor, has been tested for its ability to induce cell-cycle arrest and senescence in mesothelioma." (PMID 34226685, 2021). "We demonstrated that the antioxidant defense inhibitor auranofin and the cyclin-dependent kinase 4/6 inhibitor palbociclib could decrease mesothelioma cell proliferation alone or in combination." (PMID 37298855, 2023). "Most MPM patients could respond to CDK4/6i, which may not only arrest tumour growth but also help to convert the mesotheliomas that are rarely immunologically ‘cold’ but more frequently in intermediate inflammatory states, into ‘hot’ tumours responsive to immunotherapy." (PMID 36453028, 2024). "Such an exquisite sensitivity to CDK4/6 inhibition might be explained by the absence of oncogenic driver mutations affecting those signalling cascades in mesotheliomas, which are mostly characterized by the inactivation of tumour suppressor genes." (PMID 36453028, 2024). "However, up to now, there has been very little evaluation of CDK4/6 inhibition in mesothelioma." (PMID 37298855, 2023). "Based on these findings that potentially connect mitochondrial antioxidant defense and cell cycle pathways, we hypothesized that downregulation of Trx2 via auranofin combined with CDK4/6 inhibition via palbociclib would be more effective than either agent alone to decrease mesothelioma cell growth." (PMID 37298855, 2023). "The growth-inhibitory effects of CDK4/6 inhibition were evaluated by determining the IC50 for palbociclib and auranofin against mesothelioma cell lines H2052, H2373, H2452, and H2461." (PMID 37298855, 2023). "Another tested drug in our screen, Palbociclib, PD0332991, a CDK4/CDK6 inhibitor, that is supposed to target the most frequent deletion in mesothelioma, CDKN2A, showed only minor effects in our cell lines." (PMID 34580349, 2021). "Furthermore, lower expression of CDK7, AKT1, PARP1 (p < 0.1), CCND2 (cyclin D2), CDK2, CDK4, BIRC5 (survivin), PCNA and CDH2 (N-cadherin) (p < 0.005) have been shown to result in longer median survival of patients with mesothelioma." (PMID 36304150, 2022). "Furthermore, the combined inhibition of CDK4/6 and PI3K/AKT/mTOR pathways inhibits mesothelioma cell growth." (PMID 32033319, 2020). "Given the antitumor activity of CDK4/6 inhibitors on preclinical models of MPM cell lines and xenografts, a phase 2 clinical trial, MiST2, sought to test the clinical efficacy of abemaciclib in patients with p16ink4A-negative mesothelioma previously treated with platinum chemotherapy (NCT03654833)." (PMID 38610930, 2024). "Of note are CDK4 inhibitor (palbociclib) trials for non-mesothelioma cancer patients under way that could be repurposed for mesotheliomas." (PMID 28191281, 2016).